CD99 (CD99 molecule (Xg blood group))
Diseases named in the same sentence as CD99 in open-access papers (continued):
Sharing a sentence is not in itself a finding about the gene and the disease.
tumor (continued). "How CD99-depleted tumour cells behave during the progression of the primary tumour and its intravasation and spread is unclear." (PMID 34374417, 2021). "Increased progression of CD99-depleted tumour cells is consistent with increased migration in the absence of CD99 and the enhanced ability of CD99-depleted cells to disrupt EC barriers." (PMID 34374417, 2021). "The isolation of ES tumor cells was achieved by targeting their CD99 surface markers through immunoseparation with CD99-antibody and magnetic microbeads." (PMID 34768955, 2021). "Infiltration of ovarian tissue cryopreserved for fertility preservation purposes with ES was also described in two young patients, based on the presence of CD99 positive tumor cells harboring the EWS-FLI1 translocation." (PMID 34640378, 2021). "From a transcriptomic perspective, tumour endothelial cells upregulate angiogenesis-related genes, such as CD99, KLF10, and ADAMTS4, while losing scar tissue-related Notch molecule HES4 and antigen presentation molecule HLA-DRA." (PMID 33532508, 2021). "For extravasation, tumour cells are less efficient at attaching to the endothelium due to reduced CD99-mediated adhesion, but they have enhanced TEM activity, allowing them to seed a metastasis." (PMID 34374417, 2021). "Another tumor tissue based study, relying on well-characterized clinical cohorts, reveled CD99 as a novel clinically applicable NSCLC prognostic stromal marker." (PMID 34611477, 2021). "In conclusion, we show that cancer cell surface CD99 modulates tumour cell TEM and metastatic progression, and we identify CD99 as a negative regulator of CDC42 activity." (PMID 34374417, 2021). "Tumour cell CD99 was required for adhesion to ECs but inhibited invasion of the endothelial barrier and migratory activity." (PMID 34374417, 2021). "This xenograft model identifies a complex role for CD99 in tumour progression, with CD99 expression reducing the initial accumulation of the tumour cells in the lungs, but ultimately favouring the growth of the established metastasis." (PMID 34374417, 2021). "Immunohistochemical tests were performed and tumour demonstrated diffuse positivity for CD99, ERG, CD56 and focal positivity for Synaptophysin, PanCK, Cam5.2." (PMID 32450834, 2020). "In this work we propose β3-AR to be combined with CD99 as a possible predictor marker of recurrence or disease severity not only in the biopsy but also in circulating tumour cells." (PMID 33066095, 2020). "Most tumor cells are strongly positive for vimentin; CD99 and Bcl-2 are also expressed in some cells." (PMID 32011484, 2020). "We herein explored the molecular mechanism underlying the suppression of ligand-induced EGFR dimerization by CD99 agonists and its relevance to tumor growth in vivo." (PMID 33050232, 2020). "Investigation of CD45, CD99, and β3-ARs expression was performed on cells derived from the dissociated tumour biopsy." (PMID 33066095, 2020). "The evaluation of β3-ARs expression on tumour cells (CD45− CD99+ gated cells) revealed a higher percentage of β3-AR positive cells in samples derived from metastatic patients, with a significant statistical difference." (PMID 33066095, 2020). "Immunohistochemistry (IHC) further revealed that tumor cells were Vimentin (+), α-Inhibin (+), CD99 (+), Calretinin (+), AE1/AE3 (+), EMA (−), PLAP (−), CD117 (−), and Ki-67 (+15%)." (PMID 32629665, 2020). "IHC analysis demonstrated that tumor cells was Vimentin (+), α-Inhibin (+), CD99 (+), Calretinin (+), SF-1(+), AE1/AE3 (+), CD10 (+), ER (+), PR (+), AFP (−), EMA (−), SMA (−), CK7 (−), Ki-67 (+60%)." (PMID 32629665, 2020). "Microscopically, the tumor was composed of malignant small round cell tumor that exhibited immunoreactivity for CD99." (PMID 32158788, 2020). "To begin to develop a clinical assay based on circulating tumor derived sEVs, we opted to exploit the membranous location of CD99 and NGFR to develop a tool capable of enriching ESFT-associated sEVs from plasma in pediatric patients." (PMID 32821345, 2020).
tumor (continued). "CD99 antigen can be a useful marker for the detection and isolation of circulating tumour cells (CTCs) in EWS." (PMID 33066095, 2020). "A biopsy confirmed a small round cell tumor, and immunohistochemistry was positive for CD99 in approximately 70% of the tumor cells." (PMID 32082662, 2020). "Among these proteins, CD99 is reported to be involved in regulating tumor growth, differentiation, cell adhesion, cell migration and metastasis." (PMID 30641946, 2019). "In conclusion targeting of CD99 by vaccination inhibits tumor growth in different murine tumor models and is safe." (PMID 31001265, 2019). "In two different immunocompetent mouse tumor models we found that vaccination against CD99 reduced tumor microvessel density and functionality, and resulted in suppressed tumor growth." (PMID 31001265, 2019). "Histopathological analysis showed an almost completely necrotic tumor with a share of less than 10% viable pleomorphic tumor cells expressing vimentin and CD99 and focal positive desmin." (PMID 31426804, 2019). "The overexpression of CD99 in human tumor vasculature prompted us to study the role of the molecule in tumor growth." (PMID 31001265, 2019). "The functional assays, with U87MG CD99-shRNA, demonstrated that CD99 downregulation resulted in decreased migration and invasion of tumor cells." (PMID 30845661, 2019). "It is therefore likely that tumor growth inhibition in the CT26 model is mainly due to targeting of the tumor vasculature by the CD99 vaccine." (PMID 31001265, 2019). "Immunohistochemically, the tumor cells were positive for CD99, neuron-specific enolase, and synaptophysin." (PMID 31875190, 2019). "CD99, a glycosylated transmembrane protein, has been reported to have a marked effect on the migration, invasion, and metastasis of tumor cells through multiple and unclear action mechanisms, thereby emerging as a novel therapeutic target." (PMID 30641946, 2019). "We conclude that our observations provide an opportunity for specific targeting of CD99 isoforms in human tumor vasculature." (PMID 31001265, 2019). "In the CD99 low CT26 tumor model also a significantly lower vessel density (*P < 0.05) was found in tumors of CD99 vaccinated mice." (PMID 31001265, 2019). "Histological examination shows the tumor to be composed of diffuse compact sheet of small round cells that strongly express MIC-2 gene product (CD99)." (PMID 31377551, 2019). "Consistent with the primary tumour, immunohistochemical analyses also revealed focal positivity for CD99 and diffuse positivity for Bcl-2 and WT1." (PMID 31676869, 2019). "CD73 and CD99, detected in all three analyses of co-cultured tumor cells and fibroblasts, were the target proteins selected for this study." (PMID 31510956, 2019). "We showed that CD99 is heavily overexpressed on tumor endothelial cells in multiple human solid tumors." (PMID 31001265, 2019). "All EWS cells express the molecule at high levels, and CD99 is required for the maintenance of tumor aggressiveness." (PMID 31209202, 2019). "CD99 knockdown in EWS cells transplated into immunodeficient mice induces terminal neural differentiation and reduces tumor growth, migration and bone metastasis, supporting a central role for CD99 in the pathogenesis of EWS." (PMID 29305692, 2018). "Another potential prognostic factor for tumour aggressiveness is the neuroblast-like cell population staining positive for Ki-67 & CD99 Immunohistochemically." (PMID 30471626, 2018). "The cell surface molecule CD99 has gained interest because of its involvement in regulating cell differentiation and adhesion/migration of immune and tumor cells." (PMID 29534016, 2018). "Once the molecule is appropriately inhibited or induced, the net result is the reversion of tumor malignancy; these data establish CD99 as a promising therapeutic target for several tumors." (PMID 29305692, 2018). "Histological analysis demonstrated a small round blue cell tumor, with prominent CD99 staining of tumor cells." (PMID 29285586, 2018).
tumor (continued). "Whenever tumor cells regain CD99 expression, they become prone to reactivation of terminal differentiation programs and lose migratory and metastatic propensities." (PMID 29305692, 2018). "CD99 ligation by antibodies can increase natural killer cell-mediated tumor lysis by inducing HSP70 expression." (PMID 29534016, 2018). "CD99 is clearly involved in regulating tumor growth and differentiation and, even more importantly, in cell migration/adhesion and metastasis." (PMID 29534016, 2018). "The elucidation of the spatial and temporal control of the expression of CD99 in normal and tumor cells is required to obtain a full appreciation of this molecule and its signaling." (PMID 29534016, 2018). "The prevailing idea is that the oncogenic potential of EWS-FLI1 is facilitated by the presence of CD99: however, CD99 actively participates in the maintenance of tumor malignancy." (PMID 29534016, 2018). "After a tumor biopsy, which typically revealed the presence of “small round cell tumour” positive for neuron-specific enolase (NSE) and for CD99, all patients received neoadjuvant chemotherapy, and subsequently, they underwent surgery for tumor resection." (PMID 30005673, 2018). "Because it is expressed on specific immune and stromal cells in addition to normal and cancer stem cells, CD99 appears to be at the crossroad between the regulation of tumor cell malignancy and tumor interconnections with its microenvironment." (PMID 29534016, 2018). "In malignant gliomas, CD99 expression level is increased relative to that in normal tissues and is correlated with increased tumor aggressiveness and migration and invasion of tumor cells mediated by the Rho/Rac pathway." (PMID 29305692, 2018). "Biopsy specimen of tumor tissue revealed a proliferation of undifferentiated round cells that were CD99-positive on immunohistochemistry, so the patient was diagnosed initially with an ESFT." (PMID 30453921, 2018). "Tumor cells showed positive immunoreactivity for Vimentin and CD99 and moderate staining for Cam5.2, Syn and PR." (PMID 28472972, 2017). "After resection, the tumor’s histology and immunohistochemistry (positive for CD99, vimentin and synaptophysin) results suggested ES/PNET." (PMID 28472972, 2017). "It was reported that CD99 attenuates Src kinase activity thereby increasing tumor malignancy and metastasis." (PMID 28903388, 2017). "CD99 is critical for the pathogenesis of this tumor and it can be targeted in combination with conventional treatments." (PMID 27835596, 2016). "Abrogation of CD99 in EWS cells leads to terminal neural differentiation and severely reduces tumor growth and bone metastasis in mice, supporting a central role for CD99 in the pathogenesis of EWS." (PMID 27792997, 2016). "On the other hand, MPO positivity is a prominent feature for a tumour of myeloid origin that overrides the unusual and aberrant antigen expression (CD79a, CD99)." (PMID 27019694, 2016). "Resection of the tumor revealed a strongly CD99 positive, small, blue, round cell malignant tumor on histopathological examination that lacked the expression of lymphatic markers." (PMID 27524931, 2016). "The combination of IHC tests including LCA, vimentin, desmin and CD99 is useful to primarily assess the phenotype of the tumor cells." (PMID 27756397, 2016). "Immunohistochemically, tumor cells were diffusely positive for Vimentin and CD99, focal positive for CD34, Bcl-2 and Actin, negative for CK, EMA, Desmin, CD117, GFAP, PR and S-100." (PMID 26155787, 2015). "Immunohistochemically, tumor cells were diffusely positive for vimentin and CD99, focal positive for CD34, bcl-2 and Actin." (PMID 26155787, 2015). "Immunohistochemical examination revealed the presence of numerous tumor markers, including CD99+, Bcl-2+, partial CD34+, focal S-100+, SMA+ and CD68−." (PMID 25452776, 2015).
tumor (continued). "The tumor cells were positive for chromogranin A, synaptophysin, CD99, cytokeratin 19, pan-cytokeratin and β-catenin, and also showed diffuse immunoreactivity for AFP and human chorionic gonadotrophin." (PMID 25886790, 2015). "The tumor cells were diffusely positive for CD99, desmin, and WT1 and showed scattered focal positivity for cytokeratin." (PMID 24406431, 2014). "Immunohistochemically, tumor cells showed diffuse positivity for vimentin, CD99 and S100, while focal positivity was seen with pancytokeratin immunostain." (PMID 25395990, 2014). "The tumour cells expressed CD99 and molecular genetic investigations confirmed an EWSR1 rearrangement." (PMID 23379545, 2013). "Immunohistochemical staining of the tumor cells confirmed strong membranous expression of CD99 and focal expressions of vimentin and synaptophysin." (PMID 23537038, 2013). "In the Ewing case, the initial diagnosis was most likely based on the detection of CD99 in tumor cells." (PMID 24349741, 2013). "The immunoprofile of the tumor was CD99 (+), calretinin (+), inhibin (+), alpha smooth muscle actin (+), vimentin (+), ER (−), PR (−), keratin AE1/AE3 (−), alpha fetoprotein (−), CD117 (−), and placental alkaline phosphatase (−)." (PMID 23762714, 2013). "Immunohistochemically, the tumor was positive for CD99, vimentin, neuron specific enolase and chromogranin A, and negative for cytokeratins, CD3, desmin, and leukocyte common antigen." (PMID 23537038, 2013). "Immunohistochemical staining showed that the tumor cells were strongly positive for vimentin and CD99, focally positive for neuron specific enolase (NSE) and chromogranin A (CgA), and negative for cytokeratins, CD3, desmin, and leukocyte common antigen (LCA)." (PMID 23537038, 2013). "For example, CD99 is universally present on ES tumor cells, and immunostaining for this protein has routinely been used to confirm the diagnosis of ES in primary tumor samples." (PMID 22550426, 2012). "ES appears particularly well suited for MRD detection due to tumor-specific translocations that facilitate RT-PCR and FISH detection as well as expression of tumor-specific cell surface proteins like CD99 that facilitate detection by flow cytometry." (PMID 22550426, 2012). "By immunohistochemistry, both epithelial and spindle tumor cells were strongly positive for bcl-2 and CD99, and the spindle cells were diffusely expressed vimentin in all five cases." (PMID 22862905, 2012). "The viable tumor cells showed a strong membranous stains for CD99, focal membranous and cytoplasm stain for CD56, a cytoplasm dot pattern for synapthophysin, and focal cytoplasm and membranous stain for PGP9.5, BCL2, and vimentin." (PMID 22312368, 2012). "In one case, a dense cluster of CD34+ cells was found closely adjacent to the main tumour mass and this region colocalised with CD99+ human cells." (PMID 21779348, 2011). "Though observed in the tumour periphery, serial sections showed remarkably few CD34+ murine endothelial cells amongst the CD99+ tumor cells, Chalkley counts typically <2±0.4." (PMID 21779348, 2011). "Tumor cell staining of these masses was shown to be positive for MIC2 gene product (CD99) and neural markers such as neuron-specific enolase (NSE), vimentin, S100 protein or synaptophysin." (PMID 19830128, 2009). "The tumor cells may be arranged in Homer-Wright rosettes, and IHC often shows strong positivity for CD99 and FLI-1." (PMID 41230381, 2026). "In our case, tumor cells showed diffuse and strong membranous expression of CD99." (PMID 40950824, 2025). "In melanoma, a tumor that expresses high levels of CD99, an integrated analysis of single-cell and bulk RNA data revealed that, most significantly, melanocytes communicate with cancer-associated fibroblasts (CAFs), endothelial cells, NK cells, and T cells, as well as with macrophages." (PMID 40427525, 2025).
tumor (continued). "The CD99 molecule is found at the interface between immune cells and tumors and may play a dual role as a modulator against CD99-expressing tumor cells and immune cells." (PMID 40427525, 2025). "CD99 is a molecule with unexplored functions in tumor biology and the tumor microenvironment." (PMID 40427525, 2025). "Anti-CD99 antibodies effectively eliminate tumors and attract immune cells to the tumor area." (PMID 40427525, 2025). "Immunohistochemical studies showed that the tumor cells expressed positivity for CD99 and CD117." (PMID 40994948, 2025). "This may represent a mechanism through which tumor cells exploit CD99 expression for immune response evasion." (PMID 40427525, 2025). "CD99 overexpression also correlates with tumor hypoxia, angiogenesis, epithelial–mesenchymal transition, metabolic reprogramming, and an M2 macrophage-dominated immunosuppressive microenvironment, aiding high-CD99 tumor progression." (PMID 40427525, 2025). "Immunohistochemical studies demonstrated tumor cell positivity for CD99 and CD117." (PMID 40994948, 2025). "Immunohistochemistry showed that the tumor cells positively expressed CD99 and vimentin, some cases could positively expressed NSE, but negatively expressed S100, neurofilament protein, desmin and keratin." (PMID 41267976, 2025). "Due to its immune regulatory function, triggering CD99 may act as an immunomodulator, boosting the activity of immune cells and possibly serving as an adjuvant alongside other tumor therapies when combined with anti-CD99 antibodies." (PMID 40427525, 2025). "Since CD99 is expressed in certain pathological conditions, such as tumors and a subset of immune cells, recent research has focused on the interactions between tumor cells and TME." (PMID 40427525, 2025). "CD10 and WT1 were both diffusely positive, and CD99 was weakly positive in scattered tumour cells." (PMID 39001214, 2024). "However, in different tumor types, CD99 can act either as a tumor promoter or suppressor, with different isoforms even displaying opposite actions inside the same cell." (PMID 38785514, 2024). "They explained that the expression of CD99 in COF may be due to the neuroectodermal origin of this tumor." (PMID 39462411, 2024). "Both PAS and CD99 are positive on immunohistochemistry in the case of Askin’s tumour." (PMID 39070466, 2024). "The positive reactivity of tumor cells to CD99 in our study is in line with a previous study." (PMID 39462411, 2024). "However, the core genes that drive the enrichment score in the gene set regulated by CD99 are different from those dependent on EWS::FLI1, supporting a functional complementarity between EWS::FLI1 and CD99 in the regulation of tumor malignancy." (PMID 39524141, 2024). "As could be seen from the figure, the tumor epithelial cell subgroup C3 PLP2+ Tumor EPCs had the highest expression on the CD99 signaling pathway." (PMID 38482016, 2024). "In the IHC study, tumor cells showed positivity for CD99, EMA, vimentin, and TLE1, while they were negative for NKX2.2, WT1, BCOR, PDGFA, cytokeratins, muscle markers (smooth muscle actin, desmin, caldesmon, MyoD1, and myogenin), and melanocytic markers (HMB45, SOX10, and S100)." (PMID 38339014, 2024). "CD99 is commonly overexpressed in some tumor types, particularly in Ewing sarcoma, acute leukemias/myelodysplastic syndromes, and malignant gliomas, and more sporadically in other tumors, while it can be downregulated in other neoplasms." (PMID 38607036, 2024). "Additionally, an in vitro study using U87 MG showed that when CD99 was suppressed, tumor cell migration was decreased." (PMID 36732815, 2023). "CD99 is abnormally expressed in many different types of tumors, and plays an important role in the diagnosis, development, metastasis, and prognosis, mainly affecting the invasion and metastasis of tumor cells." (PMID 36647156, 2023).